MIR8067 (microRNA 8067)
Synonyms: hsa-mir-8067
Gene: MicroRNA gene on chromosome 15 (62,304,658 to 62,304,734, reverse strand). Ensembl gene ENSG00000277919.
Homologues: Orthologues: chimpanzee MIR8067 (100% identical).